CFAP69 (cilia and flagella associated protein 69)
Description:
Cilium- and flagellum-associated protein. In the olfactory epithelium, regulates the speed of activation and termination of the odor response and thus contributes to the robustness of olfactory transduction pathways (By similarity). Required for sperm flagellum assembly and stability.
Synonyms: C7orf63; FLJ21062; FAP69; SPGF24
Tractability: No criterion of Open Targets' tractability assessment is met for any kind of drug.
Gene: Protein-coding gene on chromosome 7 (90,245,161 to 90,311,063, forward strand). Ensembl gene ENSG00000105792.
Subcellular location: Cell projection, cilium; Cell projection, cilium, flagellum
Gene Ontology:
Biological process: flagellated sperm motility; sperm axoneme assembly; olfactory behavior; positive regulation of fertilization; positive regulation of flagellated sperm motility; response to odorant
Cellular component: cytoplasm; sperm midpiece; non-motile cilium; cilium; motile cilium
Genetic constraint (gnomAD): Loss-of-function variants: 52 observed, 65.54 expected, observed/expected ratio (o/e) 0.79, 90% interval 0.63 to 1. The upper end of that interval is the gene's LOEUF score, 1, which puts it in group 4 of 6, group 1 being the genes least tolerant of losing a copy. Missense variants: 646 observed, 651.17 expected, observed/expected ratio (o/e) 0.99, 90% interval 0.93 to 1.06. Synonymous variants: 229 observed, 221.57 expected, observed/expected ratio (o/e) 1.03, 90% interval 0.93 to 1.15.
Homologues: Orthologues: chimpanzee CFAP69 (99% identical), macaque CFAP69 (97% identical), dog CFAP69 (88% identical), pig CFAP69 (88% identical), guinea pig CFAP69 (85% identical), mouse Cfap69 (84% identical), rat Cfap69 (83% identical), rabbit CFAP69 (80% identical), tropical clawed frog cfap69 (57% identical).
Diseases named in the same sentence as CFAP69 in open-access papers:
CFAP69 is named in the same sentence as 9 diseases in open-access papers, as found by Europe PMC text mining. Sharing a sentence is not in itself a finding about the gene and the disease. The quoted sentences say what the papers report.
breast carcinoma (3 papers, 2022 to 2025). "CFAP69 has been demonstrated to be a prognostic marker that is related to the survival of breast cancer patients." (PMID 37008945, 2023). "LRRC48, CFAP69, and cg25726128 were first discovered and reported to be related to the survival of breast cancer patients." (PMID 35528180, 2022). "Furthermore, LRRC48, CFAP69, and cg25726128 were first discovered and reported to be related to the survival of breast cancer patients." (PMID 35528180, 2022).
asthenozoospermia (1 paper, 2025). "Four patients with an extreme (oligo)asthenozoospermia had one homozygous or two heterozygous pathogenic variant(s) in MMAF‐associated genes (CFAP43, CFAP69, DNAI1, and FSIP2)." (PMID 39180390, 2025).
Infertility (1 paper, 2022). "Among these mutated infertility genes, mutations of FSIP2, CFAP69, CEP19, MSH5 or MCM8 are recessive for spermatogenic failure or premature ovarian insufficiency." (PMID 35547809, 2022).
CFAP69 also shares sentences with these, for which no sentence is quoted: male infertility (3 papers); diffuse large B-cell lymphoma (1); Hydrocephalus (1); Premature ovarian insufficiency (1); spermatogenic failure (1); tumor (1).